PRSS45P (serine protease 45, pseudogene)
Synonyms: TESSP5; TESPL; formerly PRSS45
Gene: Transcribed unitary pseudogene on chromosome 3 (46,742,350 to 46,750,891, reverse strand). Ensembl gene ENSG00000188086.
Genetic constraint (gnomAD): Loss-of-function variants: 13 observed, 14.27 expected, observed/expected ratio (o/e) 0.91, 90% interval 0.59 to 1.45. The upper end of that interval is the gene's LOEUF score, 1.45, which puts it in group 5 of 6, group 1 being the genes least tolerant of losing a copy. Missense variants: 302 observed, 310.38 expected, observed/expected ratio (o/e) 0.97, 90% interval 0.88 to 1.07. Synonymous variants: 117 observed, 113.38 expected, observed/expected ratio (o/e) 1.03, 90% interval 0.89 to 1.2.